ANKH (ANKH inorganic pyrophosphate transport regulator)
Description:
Transports adenosine triphosphate (ATP) and possibly other nucleoside triphosphates (NTPs) from cytosol to the extracellular space. Mainly regulates their levels locally in peripheral tissues while playing a minor systemic role. Prevents abnormal ectopic mineralization of the joints by regulating the extracellular levels of the calcification inhibitor inorganic pyrophosphate (PPi), which originates from the conversion of extracellular NTPs to NMPs and PPis by ENPP1. Regulates the release of the TCA cycle intermediates to the extracellular space, in particular citrate, succinate and malate. Extracellular citrate mostly present in bone tissue is required for osteogenic differentiation of mesenchymal stem cells, stabilization of hydroxyapatite structure and overall bone strength. The transport mechanism remains to be elucidated (Probable).
Synonyms: ANK; HANK; CPPDD; SLC62A1; CCAL2; CMDJ; MANK
Tractability: Antibody: UniProt places it where antibodies can reach, with high confidence; its Gene Ontology location is reachable by antibodies, with high confidence; UniProt predicts a signal peptide or a membrane-spanning region. PROTAC: ubiquitination databases record sites on it.
Gene: Protein-coding gene on chromosome 5 (14,704,800 to 14,871,877, reverse strand). Ensembl gene ENSG00000154122.
Subcellular location: Cell membrane
Subcellular location (Human Protein Atlas): Cytosol
Pathways (Reactome):
Transport of small molecules: Miscellaneous transport and binding events
Gene Ontology:
Molecular function: ATP transmembrane transporter activity; phosphate transmembrane transporter activity; transmembrane transporter activity
Biological process: ATP export; locomotory behavior; regulation of bone mineralization; skeletal system development; transmembrane transport; bone mineralization; calcium ion homeostasis; cementum mineralization; diphosphate metabolic process; gene expression; inhibition of non-skeletal tissue mineralization; inorganic diphosphate transport; phosphate ion homeostasis; phosphate ion transmembrane transport; response to sodium phosphate
Cellular component: membrane; plasma membrane; outer membrane; extracellular region
Genetic constraint (gnomAD): Loss-of-function variants: 15 observed, 49.94 expected, observed/expected ratio (o/e) 0.3, 90% interval 0.2 to 0.46. The upper end of that interval is the gene's LOEUF score, 0.46, which puts it in group 2 of 6, group 1 being the genes least tolerant of losing a copy. Missense variants: 425 observed, 677.58 expected, observed/expected ratio (o/e) 0.63, 90% interval 0.58 to 0.68. Synonymous variants: 271 observed, 271.99 expected, observed/expected ratio (o/e) 1, 90% interval 0.9 to 1.1.
Homologues: Orthologues: macaque ANKH (100% identical), chimpanzee ANKH (99% identical), rabbit ANKH (99% identical), mouse Ank (98% identical), pig ANKH (98% identical), rat Ankh (98% identical), guinea pig ANKH (98% identical), dog ANKH (93% identical), tropical clawed frog ankh (92% identical), zebrafish ankhb (84% identical), zebrafish ankha (77% identical).
Diseases named in the same sentence as ANKH in open-access papers:
ANKH is named in the same sentence as 57 diseases in open-access papers, as found by Europe PMC text mining. Sharing a sentence is not in itself a finding about the gene and the disease. The quoted sentences say what the papers report.
craniometaphyseal dysplasia (12 papers, 2008 to 2025). Craniometaphyseal dysplasia (CMD) is a very rare genetic bone disease characterized by progressive diffuse hyperostosis of cranial bones causing facial dysmorphism and functional repercussions, and metaphyseal widening of long bones. "Craniometaphyseal Dysplasia (CMD) is a rare skeletal disorder that can result from mutations in the ANKH gene." (PMID 39311118, 2024). "ANKH has been linked to diseases such as Craniometaphyseal Dysplasia (OMIM: 123000) and Chondrocalcinosis 2 (OMIM: 118600), both of which are characterized by abnormal development of bones and connective tissue." (PMID 37459304, 2023). "Craniometaphyseal dysplasia has been linked to heterozygous mutations in ANKH (MIM# 123000) and biallelic mutations in GJA1 (MIM# 218400)." (PMID 35096710, 2021). "We generated four ANKH overexpression-plasmids containing either calcium pyrophosphate deposition disease or craniometaphyseal dysplasia linked mutations: P5L, E490del and S375del, G389R." (PMID 32366894, 2020). "ANKH mutations are associated with calcium pyrophosphate deposition disease and craniometaphyseal dysplasia." (PMID 32366894, 2020). "Mutations in the progressive ankylosis protein (NP_473368, human ANKH) cause craniometaphyseal dysplasia (CMD), characterized by progressive thickening of craniofacial bones and widened metaphyses in long bones." (PMID 30356088, 2018). "Pathogenic ANKH variants are a known cause of chondrocalcinosis (Online Mendelian Inheritance in Man [OMIM] #118600) and craniometaphyseal dysplasia (OMIM #123000)." (PMID 40574727, 2025). "Patients with two rare diseases {craniometaphyseal dysplasia (CMD) and familial CPPDD } have various dominant ANKH (human homolog of Ank) mutations." (PMID 19088867, 2008). "Craniometaphyseal dysplasia (MIM123000), which may be autosomal dominant or recessive, is caused by a mis-sense mutation in ANKH, which encodes the inorganic pyrophosphate channel ANK." (PMID 33193107, 2020). "However, in humans, mutations of ANKH account for craniometaphyseal dysplasia and, to the best of our knowledge, [PPi]pl levels was not yet measured in this condition." (PMID 33425894, 2020).
Arthritis (7 papers, 2011 to 2025). Inflammation of a joint. "Mutations in ANKH have been linked to ion transport disorders and inflammatory conditions, such as arthritis." (PMID 40427243, 2025). "Biallelic inactivating mutations in the progressive ankylosis gene (ANKH/Ank, humans/mice) cause a severe form of arthritis, primarily affecting joints of hands, feet and the spine." (PMID 32639996, 2020). "Recent studies have proposed ank mutations and ANKH polymorphisms, respectively, as determinants for arthritis in mice and ankylosing spondylitis in humans." (PMID 22003394, 2011). "Mutations in ANKH may lead to excessive mineralization, contributing to joint pain, arthritis, atherosclerosis, and diabetes." (PMID 40542379, 2025). "Impairment of the ANKH gene leads to excessive mineralization, including calcification of arteries leading to joint pain, arthritis, atherosclerosis, and diabetes." (PMID 38634500, 2024). "Like NUFIP2, ANKH was also reported to be involved in the pathogenesis of arthritis, immune and inflammatory response." (PMID 36591247, 2022). "The observation that mice lacking expression of ANKH develop arthritis consistent with OA at an early age further supports the hypothesis that extracellular adenosine, derived from ATP, plays a homeostatic role in cartilage." (PMID 28492224, 2017).
atherosclerosis (5 papers, 2020 to 2025). A disease characterized by the build-up of fatty material and calcium deposition in the arterial wall resulting in partial or complete occlusion of the arterial lumen. "Mutations in ANKH result in diseases associated with excessive mineralization, including calcification of arteries leading to atherosclerosis." (PMID 33192474, 2020). "In fact, the expression of ANKH was found to be decreased in human artery walls in patients with CKD or atherosclerosis." (PMID 35203651, 2022).
ankylosis (4 papers, 2012 to 2025). Fixation and immobility of a joint. "Mutations in the human progressive ankylosis gene (ANKH; Mus musculus ortholog Ank) have been identified as cause for craniometaphyseal dysplasia (CMD), characterized by progressive thickening of craniofacial bones and flared metaphyses of long bones." (PMID 27784318, 2016). "Mutations for the autosomal dominant form of CMD have been identified in the human progressive ankylosis gene (ANKH, encoding ANK), which is a known pyrophosphate (PPi) transporter." (PMID 27784318, 2016). "The role of ANKH has been defined based on a spontaneous mutation of Ank gene in a mouse model of arthritis/progressive ankylosis." (PMID 22485177, 2012). "Humans carrying a recessive mutation of ANKH gene suffer from progressive ankylosis, a joint degeneration and calcification disease caused by faulty PPi transport." (PMID 22485177, 2012). "Further evidence for a role of ANKH in the central nervous system comes from a consanguineous family where homozygosity of the ANKH missense variant (L244S) segregated with an autosomal recessive disorder comprising mental retardation, deafness, ankylosis, and mild hypophosphatemia." (PMID 40574727, 2025). "Interestingly, mild hypophosphatemia has also been associated with patients expressing a homozygous ANKH missense mutation (Leu244Ser) and presenting mental retardation, hearing loss, ankylosis, periarticular ligament ossification, enthesopathy, and dentinogenesis imperfecta." (PMID 27784318, 2016). "We show here that EC is partially mediated by a newly described plasma membrane citrate transporter ANKH/SLC62A1 (progressive human ankylosis -ANKH) in senescent fibroblasts." (PMID 40535023, 2025).
chondrocalcinosis (4 papers, 2014 to 2025). An acute episode of pain, swelling, and redness, sometimes associated with fever. "ANKH‐associated epilepsy should be considered in SeLFIE, especially in cases with a family history of chondrocalcinosis or recurrent acute joint pain episodes." (PMID 40574727, 2025).
cognitive decline (3 papers, 2023 to 2025). "Next, we tested the relevance of ANKH upregulation in senescent cell types that are relevant to age-related disease in mice, such as astrocytes (cognitive decline), adipocytes (frailty and type II diabetes), and myoblasts (frailty)." (PMID 40535023, 2025).
calcium pyrophosphate dihydrate crystal deposition disease (2 papers, 2008 to 2023). "Dominant ANKH mutations were detected in at least five multiplex families with calcium pyrophosphate dihydrate crystal deposition disease (CPPPD)." (PMID 19088867, 2008).
dementia (2 papers, 2025). Loss of intellectual abilities interfering with an individual's social and occupational functions. "The role of ANKH in age-related disease in humans has yet to be determined, but genome-wide analysis has associated the ANKH gene with a risk of developing AD, other forms of dementia, and type II diabetes." (PMID 40535023, 2025). "In addition, recent extensive genome-wide association screens revealed an association of the ANKH gene with a risk of developing Alzheimer’s disease (AD), other forms of dementia, and type II diabetes." (PMID 40535023, 2025).
maturity-onset diabetes (2 papers, 2022 to 2025). "GSEA showed that ANKH was enriched in axon guidance, glycosaminoglycan biosynthesis chondroitin sulfate, and maturity-onset diabetes of the young." (PMID 35692841, 2022).
Pseudoxanthoma elasticum (2 papers, 2020 to 2022). "In case ANKH substantially contributes to plasma PPi, it represents an attractive pharmacological target in the ectopic mineralization disorder pseudoxanthoma elasticum, which is caused by low plasma levels of PPi due to absence of functional ABCC6." (PMID 32639996, 2020). "As ANKH is part of the ectopic mineralization paradigm and appears to be downregulated in PXE fibroblasts citrate supplementation could potentially benefit pseudoxanthoma elasticum patients." (PMID 35317004, 2022).
ankylosing spondylitis (1 paper, 2023). An autoimmune chronic inflammatory disorder characterized by inflammation in the vertebral joints of the spine and sacroiliac joints. "Moreover, a regulatory role for miR-17-5p in ectopic bone formation in ligaments has been described in patients of ankylosing spondylitis, wherein it targets and suppresses the ankylosis protein homolog (ANKH) and enhances the expression of COL1A1." (PMID 37239902, 2023).
arthropathy (1 paper, 2025). Any disorder of the joints. "We suggest testing patients who are negative for common disease‐causing variants in SeLFIE (SCN2A, SCN8A, KCNQ2, PRRT2) for the ANKH c.‐11C>T change, especially if there is evidence for a familial arthropathy." (PMID 40574727, 2025).
bladder cancer (1 paper, 2007). "ANKH, which is involved in tissue calcification, was found to be amplified in bladder cancer and small cell lung cancer cell lines." (PMID 17311676, 2007).
breast carcinoma (1 paper, 2014). "All analyzed breast cancer cells depicted similar expression levels of PANX1 and ABCC1 whereas a considerable variability of ANKH and SLC22A11 expression was observed." (PMID 25496233, 2014).
cervical cancer (1 paper, 2007). A primary or metastatic malignant neoplasm involving the cervix. "Thus, upregulation of expression through amplification may be the case for TRIO, ANKH and SKP2 in some neoplasms, including cervical cancer, as indicated by our data." (PMID 17311676, 2007).
epilepsy (1 paper, 2025). A brain disorder characterized by episodes of abnormally increased neuronal discharge resulting in transient episodes of sensory or motor neurological dysfunction, or psychic dysfunction. "However, it remains unclear whether the altered function of the mutated ANKH directly causes epilepsy or interacts with other, yet unidentified pathways involved in epilepsy or neurodevelopment." (PMID 40574727, 2025). "Our study highlights the role of ANKH in epilepsy and will help to correctly diagnose infantile epilepsy more often, by shedding new light on this potentially underdiagnosed genetic form of epilepsy." (PMID 40574727, 2025).
glaucoma (1 paper, 2018). Increased pressure in the eyeball due to obstruction of the outflow of aqueous humor. "We also investigated 9 novel glaucoma-associated loci from UKB in GERA, and 6 of the novel loci replicated at Bonferroni significance (near IKZF2, CADM2, near DGKG, ANKH, EXOC2, and LMX1B)." (PMID 29891935, 2018).
gout (1 paper, 2024). A condition characterized by painful swelling of the joints, which is caused by deposition of urate crystals. "Patients with familial chondrocalcinosis type 2 (CCAL2) carrying mutations in ANKH suffer from gout-like joint pain due to calcium pyrophosphate dihydrate (CPPD) crystal deposits." (PMID 39165910, 2024).
hemochromatosis (1 paper, 2024). A disorder of iron metabolism characterized by a triad of HEMOSIDEROSIS; LIVER CIRRHOSIS; and DIABETES MELLITUS. "Patients with the ANKH gene are more susceptible to the development of CPP arthritis as are those with primary hyperparathyroidism, hypomagnesemia, and hemochromatosis." (PMID 38882993, 2024).
Intellectual disability (1 paper, 2024). "Furthermore, mutations in ANKH in humans are associated with intellectual disability in CMD patients." (PMID 39311118, 2024).
kidney stone (1 paper, 2020). "Citrate might also contribute to the mineralization inhibitory effect of ANKH, as it strongly chelates calcium and is known to prevent kidney stone (uroliths) formation." (PMID 32639996, 2020).
mild cognitive impairment (1 paper, 2025). "A recent study on a Chinese cohort reported lower methylation levels in an intronic CpG site in individuals with mild cognitive impairment or AD than in cognitively healthy controls, and we herein also found lower methylation levels in an intronic region of ANKH as a DMR in AD." (PMID 40542379, 2025).
Obesity (1 paper, 2017). Accumulation of substantial excess body fat. "ANKH is a specific bone disease-associated gene and is also reported to participate in the biological processes of obesity, thereby corresponding to our results." (PMID 29258237, 2017). "Obesity may also be linked to specific bone diseases through various functional genes, including ANKH, considering the specific contribution of ANKH in bone disease and fat accumulation." (PMID 29258237, 2017).
prostate carcinoma (1 paper, 2005). A carcinoma that arises from epithelial cells of the prostate gland. "In androgen-treated prostate cancer cell lines, the abundance of ANKH transcripts was sixfold higher than in the untreated cells." (PMID 15899038, 2005).
renal failure (1 paper, 2012). "Earlier work concentrated on bones and joints, but ANKH is also likely to have important roles in the kidney, with newer studies focusing on vascular calcification in renal failure." (PMID 23075758, 2012).
tumor (4 papers, 2007 to 2025). "Notable candidate genes included ANKH (12 associated SNPs), EIF6 (11 SNPs), and SLC4A7, DLG2, and FBXL7, which are widely implicated in cellular inflammation, immune response, and tumor development." (PMID 40427243, 2025).
bone disorder (1 paper, 2024). "Human CMD is a rare bone disorder caused by mutations in the ANKH gene." (PMID 39311118, 2024).
infection (1 paper, 2019). The state of being infected such as from the introduction of a foreign agent such as serum, vaccine, antigenic substance or organism. "It is therefore likely that AnkH is involved in altering an evolutionarily conserved eukaryotic process required for the infection by many obligate and facultative intracellular pathogens." (PMID 31455655, 2019).
ANKH also shares sentences with these, for which no sentence is quoted: cancer (3 papers); osteoarthritis (3); diabetes (2); hypophosphatemia (2); cataract (1); deafness (1); dentinogenesis imperfecta (1); disc degeneration (1); dysplasia (1); enthesopathy (1); epilepsy syndrome (1); frontometaphyseal dysplasia (1); Gaucher disease (1); ghosal hematodiaphyseal dysplasia (1); Hypomagnesemia (1); hypophosphatasia (1); Jansen’s metaphyseal chondrodysplasia (1); juvenile Paget disease (1); memory impairment (1); osteonecrosis (1); osteopetrosis (1); osteoporosis (1); osteosclerotic metaphyseal dysplasia (1); primary hyperparathyroidism (1); Pyle disease (1); sclerosteosis 1 (1); skeletal dysplasia (1); small cell lung carcinoma (1); viral infection (1).